ORAI1 (ORAI calcium release-activated calcium modulator 1)
Description:
Pore-forming subunit of two major inward rectifying Ca(2+) channels at the plasma membrane: Ca(2+) release-activated Ca(2+) (CRAC) channels and arachidonate-regulated Ca(2+)-selective (ARC) channels (Probable). Assembles with ORAI2 and ORAI3 to form hexameric CRAC channels that mediate Ca(2+) influx upon depletion of endoplasmic reticulum Ca(2+) store and channel activation by Ca(2+) sensor STIM1, a process known as store-operated Ca(2+) entry (SOCE). Various pore subunit combinations may account for distinct CRAC channel spatiotemporal and cell-type specific dynamics. ORAI1 mainly contributes to the generation of Ca(2+) plateaus involved in sustained Ca(2+) entry and is dispensable for cytosolic Ca(2+) oscillations, whereas ORAI2 and ORAI3 generate oscillatory patterns. CRAC channels assemble in Ca(2+) signaling microdomains where Ca(2+) influx is coupled to calmodulin and calcineurin signaling and activation of NFAT transcription factors recruited to ORAI1 via AKAP5. Activates NFATC2/NFAT1 and NFATC3/NFAT4-mediated transcriptional responses. CRAC channels are the main pathway for Ca(2+) influx in T cells and promote the immune response to pathogens by activating NFAT-dependent cytokine and chemokine transcription. Assembles with ORAI3 to form channels that mediate store-independent Ca(2+) influx in response to inflammatory metabolites arachidonate or its derivative leukotriene C4, termed ARC and LRC channels respectively. Plays a prominent role in Ca(2+) influx at the basolateral membrane of mammary epithelial cells independently of the Ca(2+) content of endoplasmic reticulum or Golgi stores. May mediate transepithelial transport of large quantities of Ca(2+) for milk secretion (By similarity). [Isoform alpha]: Pore-forming subunit of both CRAC and ARC channels. Couples Ca(2+) influx to NFAT-mediated transcriptional responses. [Isoform beta]: Pore-forming subunit of CRAC channels exclusively.
Synonyms: CRACM1; TMEM142A; FLJ14466; IMD9; ORAT1; TAM2
Tractability: Small molecule: a high-quality ligand is known. Antibody: UniProt places it where antibodies can reach, with high confidence; UniProt predicts a signal peptide or a membrane-spanning region; its Gene Ontology location is reachable by antibodies, with medium confidence. PROTAC: UniProt records ubiquitination sites on it; ubiquitination databases record sites on it; its protein half-life has been measured; a small molecule that binds it is known.
Target class: Ion channel; Miscellaneous ion channel; Other ion channel; Ca2+ release-activated Ca2+ channel family
Gene: Protein-coding gene on chromosome 12 (121,626,509 to 121,643,109, forward strand). Ensembl gene ENSG00000276045.
Subcellular location: Cell membrane; Basolateral cell membrane; Cell membrane (Isoform alpha); Cell membrane (Isoform beta)
Pathways (Reactome):
Hemostasis: Elevation of cytosolic Ca2+ levels
Immune System: Antigen activates B Cell Receptor (BCR) leading to generation of second messengers
Muscle contraction: Ion homeostasis
Gene Ontology:
Molecular function: calcium channel activity; identical protein binding; protein binding; store-operated calcium channel activity
Biological process: calcium ion transmembrane transport; calcium-ion regulated exocytosis; calcium-mediated signaling; positive regulation of adenylate cyclase activity; positive regulation of calcium ion transport; regulation of calcium ion transport; store-operated calcium entry; phospholipase C-activating G protein-coupled receptor signaling pathway
Cellular component: cell periphery; membrane; membrane raft; plasma membrane; plasma membrane raft; basolateral plasma membrane; calcium channel complex
Genetic constraint (gnomAD): Loss-of-function variants: 13 observed, 16.67 expected, observed/expected ratio (o/e) 0.78, 90% interval 0.51 to 1.24. The upper end of that interval is the gene's LOEUF score, 1.24, which puts it in group 5 of 6, group 1 being the genes least tolerant of losing a copy. Missense variants: 322 observed, 375.47 expected, observed/expected ratio (o/e) 0.86, 90% interval 0.78 to 0.94. Synonymous variants: 183 observed, 163.09 expected, observed/expected ratio (o/e) 1.12, 90% interval 0.99 to 1.27.
Gene-disease validity (ClinGen):
ClinGen rates the evidence that ORAI1 causes each of these diseases.
tubular aggregate myopathy (autosomal dominant): Definitive. Tubular aggregate myopathy is a disorder that affects the skeletal muscles.
Homologues: Orthologues: macaque ORAI1 (99% identical), chimpanzee ORAI1 (99% identical), pig ORAI1 (96% identical), dog ORAI1 (94% identical), rabbit ORAI1 (94% identical), mouse Orai1 (91% identical), guinea pig ORAI1 (90% identical), rat Orai1 (90% identical), tropical clawed frog orai2 (72% identical), zebrafish orai1b (61% identical), zebrafish orai1a (60% identical), Drosophila melanogaster Orai (46% identical), and 1 more. Paralogues in human: ORAI3 (53% identical), ORAI2 (53% identical).
Diseases named in the same sentence as ORAI1 in open-access papers:
ORAI1 is named in the same sentence as 255 diseases in open-access papers, as found by Europe PMC text mining. Sharing a sentence is not in itself a finding about the gene and the disease. The quoted sentences say what the papers report.
breast cancer (118 papers, 2011 to 2025). A primary or metastatic malignant neoplasm involving the breast. "Analyzing nearly 5000 patients with breast cancer revealed that the increased expression of both SigmaR1 and Orai1 channels was linked to poorer overall survival rates." (PMID 37444574, 2023). "IL6 is highly expressed in basal breast cancer cell lines, which are also associated with elevated ORAI1." (PMID 35682546, 2022). "Given the association between ORAI1 and breast cancer, ORAI1 is a possible therapeutic target in cancers with abnormal AKT signaling." (PMID 36230716, 2022). "Human Ether a-gogo potassium Channel 1 (hEag1) associates with Orai1 and regulates breast cancer cell migration through Orai1-dependent Ca2+ entry." (PMID 36612099, 2022). "Further, Kv10.1 has been reported to associate with Orai1 and to control breast cancer cell migration through Orai1-dependent Ca2+ entry." (PMID 33333945, 2020). "A similar association between SK3 and Orai1 has been observed in breast cancer cells, where it is mediated by SigmaR1, a stress-activated chaperone." (PMID 32825277, 2020). "Further association between NCS‐1 and ORAI1 was seen in breast cancer samples where a positive correlation was observed between these two genes." (PMID 31647602, 2020). "In this regard, some breast cancer cell lines exhibit augmented levels of ORAI1, SOCE and the remodeling of the calcium influx associated with invasive stimuli." (PMID 32733237, 2020). "Our analysis also showed that within basal and ER-breast cancers, higher levels of ORAI1 were associated with better relapse free survival in patients." (PMID 30754719, 2019). "Breast cancer is associated with an increased level of Orai1 and knockdown of Orai1 using siRNA in MCF-7 and MDA-MB-231 cells showed reduced SOC activity and decreased number of viable cells." (PMID 31226817, 2019). "In the current study, a robust PSO algorithm combined with the statistical analysis was used to detect the relationship between protective association of breast cancer and ORAI1 SNPs." (PMID 26380267, 2015). "Our previous studies had shown that ORAI1 is an associated gene to breast cancer with the nodal involvement, progesterone receptor status, and estrogen receptor status studies." (PMID 26380267, 2015). "In the current study, we found a strong protective association between specific combinational SNPs of ORAI1 gene in relation to breast cancer susceptibility." (PMID 26380267, 2015). "PSO analysis selected two SNPs (rs12320939 and rs12313273) in ORAI1 genes as the best protective association model against breast cancer when the genotypes of rs12320939 and rs12313273 are TT and CC, respectively." (PMID 26380267, 2015). "In our previous work, the specific combinational SNPs of ORAI1 gene were reported to be associated with breast cancer risk." (PMID 26380267, 2015). "Taken together, these results suggested that our proposed PSO strategy is powerful to identify the combinational SNPs of rs12320939, rs12313273, rs7135617, rs6486795, and rs712853 of ORAI1 gene with a strongly protective association in breast cancer." (PMID 26380267, 2015). "We used the PSO strategy to detect the protective association models between five combinational SNPs of ORAI1 gene in the breast cancer." (PMID 26380267, 2015). "Based on these data, the GA-generated SNP models to address the possible SNP-SNP interaction in ORAI1 gene were evaluated in terms of breast cancer association later." (PMID 24685237, 2014). "To develop the complex analyses of SNP-SNP interaction, we propose a genetic algorithm (GA) to detect the model of breast cancer association between five SNPs (rs12320939, rs12313273, rs7135617, rs6486795 and rs712853) of ORAI1 gene." (PMID 24685237, 2014). "For example, several individual SNPs of the ORAI calcium release-activated calcium modulator 1 (ORAI1) gene have reported to be involved in breast cancer susceptibility." (PMID 24685237, 2014).
breast cancer (continued). "In this study, the GA successfully identified appropriate models of SNP-SNP interactions in breast cancer association study in terms of five SNPs in ORAI1 gene." (PMID 24685237, 2014). "Previous studies indicated the strong correlation between breast cancer and individual single nucleotide polymorphisms (SNPs) of ORAI1 gene." (PMID 24685237, 2014). "Taken together, the cumulative effects of SNPs of ORAI1 gene in breast cancer association study were well demonstrated in terms of GA-generated SNP models." (PMID 24685237, 2014). "Knockdown of ORAI1 is anti-proliferative in MCF7 breast cancer cells and is associated with reduced activity of extracellular signal-regulated kinase (ERK1/2)." (PMID 22666335, 2012). "In this study, we provide evidence that ORAI1 SNP is associated with breast cancer-related parameters in Taiwanese breast cancer patients." (PMID 22778704, 2012). "Finally, we have studied the functional relevance of the Orai1 variants on breast cancer microcalcifications through the interaction with SPCA2." (PMID 39303919, 2024). "Using glycosylation-deficient STIM1 and Orai1 mutants we have found SOCE in breast cancer cells is insensitive to N-linked glycosylation of these proteins, a mechanism that might be relevant to evade apoptosis." (PMID 36612199, 2022). "Furthermore, Orai1 is overexpressed in gastric cancer, colorectal cancer and oral cancer, and has been associated with increased migration and invasiveness in breast cancer, colon cancer, gastric cancer and esophageal cancer." (PMID 36310590, 2022). "Despite ORAI1 being linked to several hallmarks of cancer and the activation of transcription factors, ORAI1 regulation of gene transcription, particularly in the context of breast cancer, is still poorly defined." (PMID 35682546, 2022). "Interestingly, similarly to our results, it has been shown in MDA-MB-435S (an ER− breast cancer cell line) that stores independent Ca2+ entry through Orai1, in association with potassium channel SK3 (KCa2.3), tunes calpain activation to steer cell migration." (PMID 34943998, 2021). "Indeed, one study show that the SK3, a potassium channel, associates with ORAI1 in lipid rafts and controls the constitutive calcium entry and thus bone metastasis in breast cancers." (PMID 32211326, 2020). "In addition, three studies reported multiple SNPs of ORAI1 in breast cancers, which were predicted to associate with tumor malignancy." (PMID 32211326, 2020). "Silencing TRPC6 largely reduces proliferation, survival and migration in breast cancer cell lines, which might be due to reduced expression of ORAI1 and ORAI3 in TRPC6 deficient cells." (PMID 32211326, 2020). "Our observation of poorer RFS in some breast cancer subtypes with high ORAI3 and low ORAI1 levels, is reflective of the association between the ORAI1 activators STIM1/STIM2 in basal breast cancers, where high STIM1/low STIM2 was associated with poorer survival." (PMID 30754719, 2019). "However, the SNP-SNP interaction-based association model between SNPs of ORAI1 gene and the protective association in breast cancer was less addressed." (PMID 26380267, 2015). "We hypothesized that five important SNPs within the ORAI1 gene may reduce the genetic susceptibility to breast cancer." (PMID 26380267, 2015). "The objective of this study aims to use the PSO to investigate whether combinational SNPs of ORAI1 gene in data set are protectively associated with breast cancer in the Taiwanese population." (PMID 26380267, 2015). "Therefore, we introduced the GA to optimizing the analyses of SNP-SNP interactions of ORAI1 gene associated with breast cancer." (PMID 24685237, 2014). "Therefore, we further examined the association between ORAI1 polymorphisms and the status of ER or PR hormone receptors in breast cancer patients." (PMID 22778704, 2012).
breast cancer (continued). "It is possible that weak association between ORAI1 genetic polymorphisms and the risk or tumor-related parameters of breast cancer may be due to the modest sample size, which lead to a small power in statistical analysis." (PMID 22778704, 2012). "Furthermore, both STIM1 and Orai1 were implicated in cell migration in breast cancer cells and cervical cancer cells." (PMID 22984609, 2012). "Using direct sequence for ORAI1 gene in a subset of Han Taiwanese individuals may be helpful to find novel genetic polymorphisms of ORAI1 that contribute to the development of breast cancer." (PMID 22778704, 2012). "Moreover, studies identified Orai1 calcium channel variants in MCF7 breast cancer cells, and it was shown that Orai1 variant Orai1α is essential for constitutive Ca2+ entry in MCF7 cancer cells, indicating a potential target for the formation of mammary microcalcifications in luminal breast cancer." (PMID 40236296, 2025). "Therefore, the best GA-generated SNP models of ORAI1 gene may be useful for predicting the breast cancer risk." (PMID 24685237, 2014). "Thus, the aim of this study is to investigate whether genetic variations of ORAI1 are associated with the histopathological tumor characteristics in Taiwanese breast cancer patients." (PMID 22778704, 2012). "To understand the molecular mechanism underlying this phenomenon, we measured the mRNA expression of PMCA2 and other calcium channels STIM1, ORAI-1 because of their roles in calcium homeostasis and breast cancer survival and progression." (PMID 40491474, 2025). "In MDA-MB-231 breast cancer cells, Kv10.1 silencing reduces cell migration through mechanisms involving alterations in resting membrane potential and calcium influx via Orai1." (PMID 40969934, 2025). "Luminal breast cancer cells exhibit constitutive Ca2+ entry mediated by Orai1 and the secretory pathway Ca2+-ATPase, SPCA2, which result in mammary microcalcifications that constitute a prognostic marker of mammary lesions." (PMID 39303919, 2024). "Studies have found that reducing the expression of the transcription factor Oct4 in MCF7 breast cancer cells upregulates ORAI1 expression, leading to TGF-β-stimulated EMT and promoting cell migration and invasion." (PMID 38672434, 2024). "In all investigated breast cancer cell subtypes, Orai1 is overexpressed, and its cell biology is strongly dependent on CRAC channels." (PMID 37259313, 2023). "The silencing of Orai1 by siRNA partially decreased SOCE in human breast cancer cells (MCF-7 and MDA-MB-231 cells)." (PMID 37759164, 2023). "We have found that the breast cancer stem cells (BCSC) derived from MCF7, SKBR3 and MDA-MB-231 breast cancer cell lines overexpressed Orai1 and Orai2 as compared to breast stem cells (BSC) derived from the non-tumoral cell line MCF10A (p < 0.001; n=6)." (PMID 37945647, 2023). "Biochemical and confocal microscopic studies showed that SigmaR1 physically binds to SK3 channels and that inhibiting SigmaR1 reduced SK3 and Orai1 expression in breast cancer cells." (PMID 37444574, 2023). "The Secretory Pathway Ca2+ ATPases-2 (SPCA2) interacted with Orai1 and activated store-independent calcium influx, promoting breast cancer development and progression." (PMID 36109490, 2022). "The binding of C-termini of NCL (NCL-CT) to N-termini of Orai1 (Orai1-NT) is critical for mediating calcium influx and proliferation of breast cancer cells." (PMID 36109490, 2022). "Using the ORAI1 E106Q pore dead mutant and L273D STIM1 binding-deficient mutant, our study demonstrated that ORAI1 regulation of PTGS2 and IL6 expression in basal breast cancer is dependent on both ORAI1 pore activity and STIM1 binding." (PMID 35682546, 2022). "In summary, we identified NCL as a key regulator for calcium homeostasis in breast cancer cells via activation of Orai1." (PMID 36109490, 2022). "ORAI1 levels are greater in breast cancer cells of the basal molecular subtype and is associated with increased cancer cell invasion and migration." (PMID 36230716, 2022).